INS (insulin)
Diseases named in the same sentence as INS in open-access papers (continued):
Sharing a sentence is not in itself a finding about the gene and the disease.
Hepatic steatosis (continued). "Chronic administration of any one of these FGFs results in increased insulin sensitivity, reduced hepatic steatosis (fatty liver), and improved serum lipid profiles." (PMID 26834701, 2015). "Chronic administration resulted in normoglycemia, insulin sensitization, and reduced hepatosteatosis (fatty liver)." (PMID 26834701, 2015). "We have demonstrated that while TRβ agonists effectively decrease hepatic steatosis, they drive increased insulin resistance by multiple mechanisms." (PMID 26485433, 2015). "Together, this supports an important role for altered CEACAM1-dependent insulin clearance pathways in the pathogenesis of diet-induced hepatic steatosis and visceral obesity." (PMID 26284027, 2015). "The results suggest that n-3 PUFAs rich diet ameliorates lipodystrophy-induced hepatic steatosis through reducing TG synthesis, improving insulin resistance and enhancing β-oxidation in SKO mice." (PMID 26690553, 2015). "Taurine-conjugated UDCA reduced hepatic steatosis and enhanced insulin action in mouse liver, muscle and WAT and enhanced hepatic and muscle insulin sensitivity in obese humans." (PMID 25617503, 2015). "This selectivity in directing nutrients coincides with the reduced responsiveness and sensitivity of extrahepatic tissues to insulin, i.e. insulin resistance, is thought to be markedly involved in developing ketosis and hepatic lipidosis." (PMID 26034989, 2015). "Fibroblast growth factor 21 (FGF-21) had the function of reducing blood glucose, lipid and insulin levels, reversing liver steatosis and improving insulin sensitivity." (PMID 26121037, 2015). "Previous studies have shown that choline deficiency can have impacts on glucose metabolism elicited as improved glucose tolerance and insulin sensitivity in ob/ob mice with hepatic lipidosis." (PMID 26196148, 2015). "Under the same conditions, T2 has strong lipid lowering effects and can effectively prevent hepatic steatosis, ameliorating tissue and systemic insulin sensitivity." (PMID 25538628, 2014). "Its mechanism of action involves enhanced expression of GLUT4 in skeletal muscle and diminished hepatic steatosis, both through insulin-dependent and -independent pathways." (PMID 25013446, 2014). "This is in contrast to a pediatric double-blind randomized controlled clinical trial, which demonstrated that DHA supplementation improved liver steatosis and insulin sensitivity in children with NAFLD." (PMID 25353664, 2014). "More specifically, hepatic steatosis and inflammation markedly impair the ability of insulin to inhibit liver glucose production, leading to hyperglycemia and hyperinsulinemia." (PMID 25147439, 2014). "Significant alterations in the gut microbiota have been shown to affect body weight and other metabolic processes such as bile-acid metabolism and subsequent intestinal lipid absorption, insulin sensitivity, and hepatic steatosis." (PMID 25517731, 2014). "The offspring of the dams fed the high-fat diet had a heavier body weight, impaired glucose tolerance, decreased insulin sensitivity, increased serum cholesterol and hepatic steatosis at weaning." (PMID 25158235, 2014). "The observed leptin: adiponectin ratios and hepatic steatosis were also consistent with the establishment of an insulin-resistant state." (PMID 25013446, 2014). "Overflow of NEFA from obese, insulin resistant adipose tissue to liver contributes to hepatic steatosis and resultant IR, an effect which is markedly improved upon disruption of ATM recruitment." (PMID 25412423, 2014). "Hormonal regulation of PPARγ activity has been previously demonstrated in cases where PPARγ activity was stimulated by insulin treatment, and furthermore, its overexpression led to hepatic steatosis." (PMID 24789994, 2014). "FGF21 improves hepatic steatosis and insulin sensitivity in obese mice by stimulating lipolysis and fatty acid oxidation and reducing gluconeogenesis." (PMID 24935677, 2014).
Hepatic steatosis (continued). "Metabolic improvement was indicated by increased glucose tolerance and insulin sensitivity and a marked resolution of hepatic steatosis." (PMID 24033924, 2014). "While there is a compelling correlation between mitochondrial dysfunction and fatty liver disease, the molecular pathways directly linking altered mitochondrial function, insulin resistance, and inflammation are still unclear." (PMID 24672550, 2014). "According to prior studies, about 5~10% (w/w) fiber in the diet, an average of 1~3 g fiber intake, can effectively improve symptoms of fatty liver disease by insulin regulation, antioxidation, and lipid-lowering action." (PMID 25520925, 2014). "Higher hepatic fat accumulation leads to increased SGPT and SGOT values, which lead to the development of fatty liver disease and hepatic inflammation due to the dysfunction of insulin target cells and resulting imbalance of lipid metabolism." (PMID 25053966, 2014). "Discrepant effects on insulin sensitivity and hepatic steatosis have been observed in several recent studies." (PMID 23951308, 2013). "These mice showed improvements in insulin sensitivity, hepatic steatosis, and normal glucose and insulin levels." (PMID 23876211, 2013). "This leads to enhanced circulating insulin sensitivity, normalizes blood glucose, and suppresses the progress of hepatic steatosis." (PMID 23762873, 2013). "In parallel with increased body weight, body fat mass, serum lipid profiles, insulin and hepatic steatosis were elevated in both HL/HL and HS/HS at the end of experiment, but were increased to a greater extent in HL/HL group." (PMID 24223162, 2013). "Along with improvements of liver insulin sensitivity, obese Nlrp3−/− and Asc−/− mice exhibit reduced hepatic steatosis compared to wild type controls." (PMID 23483669, 2013). "DHA supplementation (250–500 mg/day) significantly improved liver steatosis and insulin sensitivity in an RCT in children (n = 60)." (PMID 24152749, 2013). "These local alterations in adipose tissue inflammation and expansion correlated with a lower liver size, less hepatic steatosis, and preserved insulin sensitivity." (PMID 23341960, 2013). "In this study, we demonstrated that BM-V reduced plasma FGF21 levels and hepatic FGF21 content, and attenuated HFD-induced liver steatosis, while BM-V also significantly enhanced peripheral insulin sensitivity." (PMID 24189525, 2013). "ViLVaL improved insulin signaling and attenuated stress signaling in liver with amelioration of hepatic steatosis due to activated fatty acid oxidation in db/db mice." (PMID 24188631, 2013). "Ectopic fat accumulation and adipose tissue–derived inflammatory mediators, then contribute to hepatic steatosis, hepatic insulin resistance, and augmented pyruvate-glucose flux." (PMID 23341960, 2013). "HCTZ treatment worsened hepatic steatosis measured as hepatic TG content and reduced insulin sensitivity." (PMID 23837919, 2013). "This study was conducted in the case of CCl4-induced hepatic steatosis; it would be interesting to investigate the effect of EUCE on high-fat high-sugar diet-induced hepatic steatosis and hepatic insulin resistance." (PMID 24223588, 2013). "Complementarily, IL-1β knockout mice were more insulin sensitive on either normal chow or high fat diet, and both IL-1β and IL-1α knockouts were protected against hepatic steatosis induced by high fat or atherogenic diets." (PMID 23341960, 2013). "With regard to LTKO mice, although they have better insulin sensitivity after 5 months of high-fat treatment, those mice also developed hepatic steatosis as we previously reported." (PMID 24015318, 2013). "The administration of rosuvastatin (20 mg/kg/day) improved the insulin sensitivity, decreased the liver steatosis and the body weight, and improved the circulating levels of cholesterol and triglycerides in mice fed a HF diet." (PMID 23816341, 2013).
Hepatic steatosis (continued). "Protection against both HFD and ER stress-induced hepatic steatosis is likely to contribute to increased hepatic insulin sensitivity in KLF15-/- mice." (PMID 24167585, 2013). "Previous studies showed that the FAT diet decreases insulin sensitivity, while the high ratio of saturated fatty acid induces hepatic steatosis and hepatic IR." (PMID 24044579, 2013). "Yet, rats overexpressing ChREBP, fed on a standard diet, developed hepatic steatosis but remained insulin sensitive, despite increased expression of genes involved in lipogenesis/fatty acid esterification." (PMID 24264040, 2013). "HCTZ treatment worsened hepatic steatosis measured as hepatic triglyceride content and reduced insulin sensitivity." (PMID 23837919, 2013). "In conclusion, a maternal obesogenic diet-induced postpartum impaired insulin sensitivity, hepatic steatosis and contributed to a programmed neonatal hepatic inflammatory profile." (PMID 24146946, 2013). "Mice deficient in Cidea or Cidec have been shown to exhibit reduced hepatic lipid accumulation and improved insulin sensitivity, while overexpression of Cidea in mouse liver promoted hepatic steatosis." (PMID 23505504, 2013). "In summary, the present study suggested lard oil rich in SFA can promote severer ER stress, inflammation, hepatic steatosis and insulin resistance than soybean oil rich in polyunsaturated fatty acid." (PMID 24223162, 2013). "Activation of PPARα that is in particular highly expressed in liver, is a well-established strategy for treating metabolic diseases including fatty liver, which can systemically also have beneficial effects on insulin sensitivity." (PMID 24265809, 2013). "Treatment with thiazolidinediones reduces hepatic steatosis by 30–50% by modulating insulin sensitivity and endocrine function of adipose tissue in T2DM." (PMID 22761701, 2012). "Systemic insulin sensitivity was slightly improved in those mice suggesting that the improved insulin sensitivity in muscles was sufficient to overcome the enhanced liver steatosis and adipose tissue inflammation." (PMID 23316186, 2012). "Our in vivo models of hepatic steatosis with perturbed insulin concentrations had relatively increased IRS-1 expression at high insulin concentrations (T2FLD), and relatively increased IRS-2 at low insulin concentrations (T1FLD)." (PMID 22745692, 2012). "Activation of key ER stress signalling molecules has also been shown to enhance lipogenesis, contributing to hepatic steatosis and insulin resistance." (PMID 22355328, 2012). "Our results suggest that insulin resistant women with recent GDM, have an increased risk for presence of fatty liver." (PMID 22393439, 2012). "Since t-10, c-12 CLA supplementation induced significant liver steatosis and hepatomegaly, and marked changes in plasma adiponectin and insulin levels, a three week study was undertaken." (PMID 23285120, 2012). "The main finding of this report is that the amount of circulating insulin is a major modulator of hepatic steatosis via regulation of liver fatty acid transport proteins." (PMID 22745692, 2012). "In conclusion, the present study demonstrated that ingestion of a diet high in fat and sucrose by mice significantly elevated WAT weights, hepatic steatosis, and plasma insulin levels as early as 2 weeks." (PMID 22762794, 2012). "The present study investigated their roles in the development of hepatic steatosis and insulin resistance during de novo lipogenesis (DNL) compared to extrahepatic lipid oversupply." (PMID 22355328, 2012). "We also examined the effects of these treatments on factors known to play a role in the development of hepatic steatosis including peripheral insulin sensitivity, hepatic FAO, and markers of hepatic lipogenesis." (PMID 21918718, 2012).
Hepatic steatosis (continued). "A HF induced hepatic steatosis with significant increases in the serum levels of free fatty acids (FFAs), triglyceride (TG), total cholesterol (TC), and insulin." (PMID 22458550, 2012). "In conclusion, our study documents the detrimental effects of overeating while remaining sedentary on adiposity, insulin sensitivity, hepatic mitochondrial function, and hepatic steatosis." (PMID 21918718, 2012). "When these two palmitoleate-driven events occur simultaneously, palmitoleate induces hepatic steatosis while increasing insulin signaling." (PMID 22768070, 2012). "High consumption of dietary fructose is an important contributory factor in the development of hepatic steatosis in insulin or leptin resistance." (PMID 22991573, 2012). "In contrast, short-term inhibition of tissue specific hepatic SCD increased hepatic TG content and enhanced insulin signaling, but the long-term inhibition decreased hepatic steatosis." (PMID 21869929, 2012). "As previously reported, the combined therapy had greater effect to increase insulin sensitivity and to improve hepatic steatosis than monotherapy in the MCDD rat model of NAFLD." (PMID 22536512, 2012). "Adenosine receptors have been studied in the context of insulin homeostasis and glucose metabolism, lipolysis, development of hepatic steatosis, and reverse cholesterol transport." (PMID 22848385, 2012). "Following reduction in the amount of insulin the metabolism of acids in the liver is disrupted and eventually fatty liver is resulted which is followed by increases in ALT, AST, and ALP levels (Bush 1991 ▶; Jelodar, Nazifi, 1997 ▶)." (PMID 25050245, 2012). "In an ovine model of prenatal maternal androgenization, we report the occurrence of hepatic steatosis, alterations in hepatic metabolic gene expression and perturbations in insulin secretion in young adults." (PMID 21935484, 2011). "Mice with a disruption in SCD-1 (stearoyl-CoA desaturase 1) have reduced adiposity, resistance to diet-induced weight gain, reduced hepatic steatosis, and increased insulin sensitivity." (PMID 21698093, 2011). "Although fructose-feeding has been shown to induce impaired insulin action and increased hepatic steatosis in several rodent species including rats and hamsters, C57Bl/6 mice appear comparatively resistant to carbohydrate-induced effects." (PMID 21261970, 2011). "The data herein demonstrate that improvement of glucose tolerance and hepatic steatosis by leucine supplementation correlates with improved insulin signaling in muscle, liver and fat." (PMID 21731668, 2011). "The beneficial effects on hepatic steatosis are likely a consequence of increased insulin sensitivity through reduced peripheral lipolysis, inhibition of lipid synthesis, and stimulation of FA oxidation." (PMID 21918648, 2011). "In conclusion, we demonstrated that TACE-activity inhibition by Marimastat in two murine models of hepatic steatosis resulted in reversal of steatosis, coupled with improvement of surrogate markers of insulin sensitivity." (PMID 21980496, 2011). "Qualitative analysis of liver histology sections found a trend towards increased focal and disseminated hepatic steatosis in insulin resistant baboons when compared to insulin sensitive baboons, as determined by both QUICKI and clamp results." (PMID 22125617, 2011). "In obese and diabetic patients, hepatic steatosis results in a failure of insulin action and consequently leads to excessive hepatic glucose production (HGP) and fasting hyperglycemia." (PMID 20574539, 2010). "Thiazolidinediones increase insulin sensitivity and decrease hepatic steatosis and inflammation in humans, but they have several side effects including weight gain, heart failure, and increased fracture risk." (PMID 21079772, 2010). "Ezetimibe improved hepatic insulin signaling as well as hepatic steatosis in Zucker Obese fatty (ZOF) rats." (PMID 19821987, 2009).
Hepatic steatosis (continued). "These insights may ultimately facilitate the development of mitochondrial-targeted therapeutics to mitigate hepatic steatosis, improve insulin responsiveness, and preserve overall liver function in at-risk patient populations." (PMID 41543486, 2026). "SGLT2 inhibitors improve insulin sensitivity, reduce hepatic steatosis and liver enzymes." (PMID 41071622, 2026). "Similarly, pharmacologic blockade of 5-HT4 receptors (GR113808) prevents weight gain, insulin resistance, hepatic steatosis and inflammation induced by HFD in mice." (PMID 41424854, 2026). "In turn, chronic DRN neuron activation or chronic intranasal administration of 5-HT improves hepatic lipid metabolism, reduces liver steatosis, and ameliorates systemic (muscle) tolerance to glucose, and hepatic and systemic (muscle) sensitivity to insulin 93,97." (PMID 41424854, 2026). "Co-administration improved parameters such as body weight, adipocyte hypertrophy, insulin sensitivity, lipid profiles, hepatic steatosis, vascular function, and the expression of inflammation and oxidative stress, achieving effects not observed with each supplement alone." (PMID 41596333, 2026). "Additionally, further analysis indicated that RC/HDL-C ratio was an independent risk factor for GDM, which persisted even after adjusting for insulin, fasting glucose, and hepatic steatosis." (PMID 39752447, 2025). "Additionally, SOCS3 is closely related to IR development, as its overexpression in the liver leads to IR, while its inhibition enhances insulin sensitivity and ameliorates hepatic steatosis." (PMID 40520339, 2025). "Notably, HIIT exhibited superior efficacy in improving insulin sensitivity, hepatic steatosis and BAT remodeling, whereas MICT showed greater potency in WAT remodeling." (PMID 40305497, 2025). "Additionally, dexmedetomidine (DEX) improved insulin sensitivity and reduced hepatic steatosis and inflammation in MASLD mice by lowering SCD1 levels." (PMID 40004240, 2025). "In addition, previous studies have shown that adiponectin can reduce IR and liver steatosis, with additional anti-inflammatory, anti-apoptotic, and insulin-sensitizing properties, whereas TNF increases IR and has pro-inflammatory effects." (PMID 40002806, 2025). "Moreover, dietary MUFAs can activate PPARα, increasing lipid oxidation, and reducing resistance for insulin resulting in hepatic steatosis reduction." (PMID 41144456, 2025). "Moreover, previous studies suggested the TyG index is more reliable than insulin level and HOMA-IR, a predictor and diagnostic tool of hepatic steatosis." (PMID 40429560, 2025). "However, DNL is jointly driven by both PP and PC regions, and disruption of insulin signaling in either region can reduce overall hepatic DNL levels and attenuate the risk of high-fat-diet–induced hepatic steatosis." (PMID 40950956, 2025). "Although CK2α ablation exerted little response in LFD‐fed mice, it markedly alleviated HFD‐induced changes, including hepatic architectural alterations, liver steatosis, blood profiles indicative of liver injury, lipid droplet formation, plasm insulin levels, and the HOMA‐IR index." (PMID 40656543, 2025). "It offers beneficial effects, including reductions in body weight, hepatic steatosis, and serum lipid levels (such as triglycerides and cholesterol), while also improving insulin sensitivity and liver enzyme levels (ALT, AST) in models fed a high-fat diet (HFD)." (PMID 41257640, 2025). "While current clinical management of NAFLD primarily relies on lifestyle modifications and metabolic regulation interventions—including insulin sensitizers, antioxidants, and lipid-lowering agents—these approaches can delay disease progression but rarely reverse hepatic steatosis and fibrosis." (PMID 41383472, 2025).